BRAF (B-Raf proto-oncogene, serine/threonine kinase)
Diseases named in the same sentence as BRAF in open-access papers (continued):
Sharing a sentence is not in itself a finding about the gene and the disease.
colorectal adenocarcinoma (continued). "The other six cell lines are colorectal adenocarcinoma cell lines: DLD-1 and HCT116 bear KRAS and PI3KCA mutations, SW620 bears KRAS mutation, HT29 and RKO bear BRAF and PI3KCA mutations and Colo205 cell line bears BRAF mutation." (PMID 27520705, 2016). "Given that KRAS and BRAF are part of the RAS-RAF-MAPK signaling pathway frequently altered in colorectal adenocarcinoma, these findings support the hypothesis that NECs and adenocarcinoma components may be clonally related and originate from a common precursor cell." (PMID 41153242, 2025). "Thus, finding an effective way to inhibit the expression of these proteins while sustaining SPINK1 levels might have a clinical benefit in BRAF V600E‐positive colorectal adenocarcinoma." (PMID 29193645, 2018). "Frequent genetic mutations found in colorectal adenocarcinoma are not exhibited by GCA, which are usually negative for BRAF, KRAS and SMAD4." (PMID 40729214, 2024). "In this study, anti-tumour activity of new SMAC-mimetics Birinapant and AT-406 is evaluated against colorectal adenocarcinoma cells and IAP cross-talk with either oncogenic BRAF or BCL-2, or with the TRAIL are further exploited towards rational combined protocols." (PMID 27520705, 2016). "Multiple authors reported no Epidermal growth factor receptor, BRAF, KRAS, or Adenomatous polyposis coli (APC) mutations in GCA, suggesting that its molecular pathogenesis is significantly different from that of colorectal adenocarcinoma, although again this was not a unanimous finding." (PMID 35903705, 2022). "In colorectal adenocarcinoma (COREAD), two cell lines (KM12 and LS-513) do not respond to the BRAF inhibitor PLX-4720, despite being BRAF mutants." (PMID 33205120, 2020).
Hashimoto thyroiditis (44 papers, 2012 to 2026). An autoimmune disorder caused by the production of autoantibodies against thyroid tissue. "Hashimoto’s thyroiditis was present in 17.6% of patients, and BRAF V600E mutations were identified in 43.3% of cases." (PMID 40084143, 2025). "The independent variables in our final predicting model encompassed diameter, Hashimoto’s thyroiditis, BRAF V600E mutation status, ill-defined margin, echogenic foci, and the suspicion of cervical lymph node metastasis based on US." (PMID 39568807, 2024). "Fine needle aspiration cytology (FNAC) showed PTC with Hashimoto's thyroiditis and BRAF V600E mutation after thyroidectomy and lymph node dissection." (PMID 36743683, 2023). "Comorbid Hashimoto’s thyroiditis developed in 86 patients and mutation of BRAF V600E gene occurred in 163 patients." (PMID 35547002, 2022). "In contrast, sex, age, ETE, capsular invasion, BRAF mutation, Hashimoto thyroiditis, and lateral lymph node metastasis were insignificantly associated with contralateral occult PTC." (PMID 34322091, 2021). "Coexistent Hashimoto’s disease was found in 103 (28.9%) patients and BRAF 600E mutations were noted in 257 (72.0%) patients." (PMID 34040587, 2021). "The BRAF V600E (+) Warthin-like variant (WV), frequently associated with Hashimoto’s thyroiditis (HT) (93% to 100% of all cases) presents with US features of malignancy, suchas solid composition, hypoechogenicity, and taller-than-wide shape." (PMID 34070605, 2021). "In classic PTC, the frequency of BRAF mutations was negatively correlated with coexisting Hashimoto's thyroiditis." (PMID 25983754, 2015). "Furthermore, BRAF 1799T>A was underrepresented in PTCs with chronic lymphocytic thyroiditis (CLT), and cyclin A expression was associated with increased PTC tumor size." (PMID 32092888, 2020). "However, WLPTCs were more commonly associated with Hashimoto's thyroiditis than classic PTCs (93% versus 36%, resp., P < 0.001) and showed significantly lower rate of BRAF mutation when compared to classic PTCs (65% versus 84%, resp., P = 0.007)." (PMID 25983754, 2015). "Hashimoto’s thyroiditis was determined to be an independent protective factor against recurrence only in patients with BRAF-wild type carcinomas." (PMID 37190300, 2023). "Consistent with this indication, the presence of Hashimoto's thyroiditis, which is considered to be a protective factor in PTC patients, was significantly associated with BRAF V600E-negative patients." (PMID 35755312, 2022). "The BRAF V600E status, gender, family history, concomitant multinodular goiter, Hashimoto thyroiditis, multi-focality, multi-centricity, post-operative thyroglobulin level, and extent of neck dissection were tested." (PMID 34734568, 2021). "A high frequency of older patients (p value: 0.004) was observed among the BRAF-mutated PTC group and, in contrast, a low frequency of concurrent Hashimoto's thyroiditis (HT) (p value: 0.011) was noted." (PMID 30916170, 2019). "For instance, the presence of chronic lymphocytic thyroiditis and BRAF V600E, which have been shown to exhibit sex-based differences, could serve as potential confounders." (PMID 40705743, 2025). "In our set, neither BRAF V600E mutation nor coexisting Hashimoto’s thyroiditis showed significant differences in univariate analysis." (PMID 41473251, 2025). "The tissue ratio accurately diagnosed thyroid malignancy regardless of BRAF mutation or Hashimoto's thyroiditis status, overcoming genetic and autoimmune heterogeneity." (PMID 38001954, 2023). "In 2014, a study in Korea showed that presence of BRAF V600E alleles had a significant association with extrathyroidal extension, absence of chronic lymphocytic thyroiditis, and increased tumor size." (PMID 36743179, 2022). "The BRAF V600E mutation was present in 1102 (87.7%) of the 1257 patients and was significantly associated with older age, conventional subtype, multifocality, advanced TNM stage, and a reduced prevalence of Hashimoto's thyroiditis." (PMID 35755312, 2022).
Hashimoto thyroiditis (continued). "Clinicopathological factors that may affect the BRAF mutation rate in PTC are age, sex, histologic variants, tumor size, extrathyroidal extension, multifocality, and Hashimoto thyroiditis." (PMID 31212879, 2019). "Interestingly, Hashimoto's thyroiditis (HT) was more commonly seen in patients with wild-type BRAF tumors (P < 0.001)." (PMID 26943032, 2016). "Furthermore, in a previous study, 13 of the PTC patients who underwent BRAF testing and showed no mutations were complicated with Hashimoto’s Thyroiditis (HT)." (PMID 38218832, 2024). "At the molecular level, upregulation of the RET/RAS/BRAF/ERK/MAPK pathway, which has the capability to induce both a proinflammatory and a protumourigenic thyroid programme, is a possible mechanism linking chronic thyroiditis with carcinogenesis." (PMID 28572821, 2017). "Age, gender, microscopic ETE, diameter of the largest tumor, total diameter of all tumors, multifocality, bilaterality, presence of chronic thyroiditis, variants of PTMC, BRAF mutation, and LLND were not predictors of recurrence." (PMID 28741199, 2017).
fibrosarcoma (42 papers, 2012 to 2025). A malignant mesenchymal fibroblastic neoplasm affecting the soft tissue and bone. "The BRAF-V600E (B-rapidly accelerated fibrosarcoma) mutation is an activating mutation leading to the constitutive activation of the RAS-RAF-MEK-ERK-MAPK pathway." (PMID 39958088, 2025). "This study aims to explore the clinical features, diagnosis, and treatment of infantile fibrosarcoma (IFS) associated with BRAF mutations, with the goal of enhancing clinicians’ understanding of this rare genetic variant and its relationship to IFS." (PMID 39959667, 2025). "The KRAS/B-rapidly accelerated fibrosarcoma (BRAF)/microsatellite instability (MSI) genetic mutation test showed that the patient had a wild-type KRAS/BRAF and MSI-low status." (PMID 40130130, 2025). "Here we present a unique case of a normal-weight, full-term girl with spontaneous intestinal perforation due to a spindle cell neoplasm with a novel BRAF mutation and infantile fibrosarcoma-like morphology." (PMID 36090580, 2022). "BRAF V600 is an activating mutation, which results in high kinase activity and overproduction of active oncoproteins such as rapidly accelerated fibrosarcoma (RAF)." (PMID 33704186, 2020). "In particular, in homozygous recessive patients for Fok1 SNPs of VDR a high rate of histological regression and BRAF (B- Rapidly Accelerated Fibrosarcoma gene) mutation were observed." (PMID 29100280, 2017). "Notably, BRAF fusions and point mutations including p.V600E/D were also detected in cases of infantile fibrosarcoma." (PMID 39387892, 2024). "In addition to BRAF mutations, NRAS p.Q61K has been detected in a BRAF wild-type ameloblastic fibrosarcoma sample." (PMID 35048058, 2021). "BRAF belongs to the “rapidly accelerated fibrosarcoma” (RAF) family of mammalian cytosolic serine/threonine kinases, comprising ARAF, BRAF, and CRAF, which function in the mitogen-activated protein kinase (MAPK) signalling pathway downstream of RAS." (PMID 38787171, 2024). "Activating genetic events in BRAF (missense substitutions, rearrangements) have been also described in infantile fibrosarcomas and tumors classified as NTRK-Rearranged Spindle Cell Neoplasms by the 5th Edition of the WHO Classification of Tumors (2020)." (PMID 39018206, 2024). "In particular, BRAF alterations result in constitutive activation of the rapidly accelerating fibrosarcoma–extracellular signal–regulated kinase–MAPK significant pathway, leading to cellular proliferation, survival, and dedifferentiation." (PMID 37124503, 2023). "The V-Raf Murine Sarcoma Viral Oncogene Homolog B (BRAF) oncogene, localized on chromosome 7q34, encodes for a serine–threonine protein kinase belonging to the rapidly accelerated fibrosarcoma (Raf) protein family (which also includes ARAF and CRAF proteins)." (PMID 33260892, 2020). "Such treatments were considered in 15 of the 23 NSCLC dossiers for the following mutations: anaplastic lymphoma kinase (ALK), rapidly accelerated fibrosarcoma-isoform B (BRAF), epidermal growth factor receptor (EGFR) and the C-ros oncogene 1 (ROS1)." (PMID 32236766, 2020). "The v-raf murine sarcoma viral oncogene homolog B1 (BRAF) is one of three RAF genes (rapidly accelerated fibrosarcoma A, B, C) localized on chromosome 7q34." (PMID 24410877, 2014). "Given the suspicion of pediatric fibrosarcoma and the negativity for panTRK, fluorescence in situ hybridization (FISH) was performed for the BRAF gene, revealing an EVI5::BRAF fusion." (PMID 39940949, 2025). "Rapidly accelerated fibrosarcoma (ARAF, BRAF, CRAF) kinase is central to the MAPK pathway (RAS–RAF–MEK–ERK)." (PMID 37625591, 2023). "Recently, it has been discovered that RGS can interfere with RAS-signaling by binding to the RAS binding domains (RBD) of RAS-effector proteins (such as the rat fibrosarcoma (RAF) isoforms (ARAF, BRAF, and CRAF) and phosphatidylinositol 3-kinase (PI3K))." (PMID 29423069, 2018). "In addition, a fusion of BRAF and ADCK2 has been detected in infantile fibrosarcoma." (PMID 35205819, 2022).
fibrosarcoma (continued). "A congenital fibrosarcoma with PRKAR1B::BRAF fusion was found by histological analysis: PRKAR1B encodes a regular subunit of the cyclin AMP-dependent protein kinase A complex, implicated in neurodegenerative dementia but not well associated with cancer, while B-RAF is a well-known proto-oncogene." (PMID 41245797, 2025).
lymphoma (41 papers, 2012 to 2026). A malignant (clonal) proliferation of B- lymphocytes or T- lymphocytes which involves the lymph nodes, bone marrow and/or extranodal sites. "The NCI-MATCH study reported an ORR of 38% (90% CI: 22.9, 54.9; P < 0.0001) with dabrafenib plus trametinib in patients with BRAF V600E/D/R/K mutation-positive solid tumors, lymphomas or MM whose disease had progressed on at least one standard therapy." (PMID 37059834, 2023). "With that backdrop, we studied trametinib, a second-generation allosteric inhibitor of MEK1/2 in patients with solid tumors and lymphomas harboring mutations in BRAF outside the V600 codon, as well as BRAF fusions." (PMID 33216832, 2020). "The next-generation sequencing performed on the sample confirms that the predominant T-cell clones in this lymphoma contained CAR-T cell fusion mRNA, with potential driver mutations found in TET2, BRAF (V600E), PPM1D, ATM, and RUNX1." (PMID 41509667, 2026). "For example, the BRAF pseudogene functions as a ceRNA to upregulate BRAF expression by sequestering shared microRNAs, promoting lymphoma development." (PMID 41602364, 2026). "Regarding ceRNAs of pseudogenes, these contribute to oncogenesis, as the BRAF pseudogene does in lymphoma, as well as other ceRNAs in colorectal, breast, ovarian, and among other types of cancer." (PMID 38397997, 2024). "Common enriched mutations and cancer tissue types found across these examples include BRAF and RB1 mutations as well as skin, small-cell lung cancer, lymphoma, and leukaemia tissue types, respectively." (PMID 31602313, 2019). "Overexpression of oncogenic BRAF in lymphoma cell lines showed that it rendered lymphoma cells against venetoclax resistance, in vitro." (PMID 29463802, 2018). "The pseudogene BRAFP1 regulates BRAF expression through functions as a ceRNA and competitive binding of miR-30a, miR-182, miR-876, and miR-590, which finally Induces lymphoma in vivo." (PMID 28029651, 2017). "Four samples of lymphoma were found to have gain of BRAF gene by CNV analyses in both frozen and FFPE tissues." (PMID 24699316, 2014). "The mitochondrial remodelling in KRAS mutated–BRAF wild-type CRC agree with Warburg’s hypothesis, suggesting that the scenario might be different to that observed in other tumours, as in the case of the relevant role of OXPHOS in lymphomas." (PMID 34439343, 2021). "It should be highlighted that MET, KDR (VEGFR) STK11 and BRAF are all upstream signaling components in the MAPK pathway and aberrant MAPK signaling is a known oncogenic mechanism in lymphoma." (PMID 29854308, 2018). "Similarly, BRAF pseudogene 1 (BRAF1) upregulated its cognate BRAF by competitively interacting with shared miRNAs, promoting lymphoma." (PMID 33933142, 2021). "A similar pattern was observed in the lymphoma cell line SUD-DHL-4 V, which does not harbor mutations in KRAS and BRAF." (PMID 26799289, 2016).
papillary carcinoma (41 papers, 2004 to 2026). A malignant epithelial neoplasm characterized by a papillary growth pattern. "The only PTC with a BRAF non p.V600E exon 15 mutation carried BRAF p.V600A, an RAS-like BRAF exon 15 mutation compatible with the diagnosis of encapsulated follicular variant papillary carcinoma." (PMID 32059434, 2020). "Other far less common BRAF alterations include nucleotide changes associated with follicular patterned tumors (follicular adenoma, follicular carcinoma, and encapsulated follicular variant papillary carcinoma) and rearrangements associated with radiation-induced PTCs." (PMID 32059434, 2020).
Papillary Craniopharyngioma (41 papers, 2015 to 2026). A craniopharyngioma composed of sheets of squamous epithelium which separate to form pseudopapillae. "Papillary craniopharyngioma is a rare entity, demonstrating BRAF-V600E mutations in approximately 95% of patients." (PMID 39976897, 2025). "The prevalence of BRAF mutation in papillary craniopharyngioma (PCP) and the positive response with BRAF-MEK inhibitors have shifted the treatment paradigm towards targeted therapy." (PMID 39937275, 2025). "In the past decade, the strong association between the BRAF V600E mutation and papillary craniopharyngioma diagnosis has prompted discussion regarding utilization of BRAF and MEK inhibitors as treatment." (PMID 39976897, 2025). "Histopathologic and genomic analysis of the lesion was consistent with papillary craniopharyngioma with the BRAF V600E mutation." (PMID 39976897, 2025). "Histopathologic and genomic analyses were consistent with papillary craniopharyngioma harboring the BRAF V600E mutation." (PMID 39976897, 2025). "Most sellar or suprasellar papillary craniopharyngiomas have BRAF V600E mutations recognized by the VE1 antibody." (PMID 39939491, 2025). "Although PCP was previously thought to be exclusive to adults, the identification of BRAF V600E mutations has confirmed the existence of pediatric papillary craniopharyngiomas (PPCP)." (PMID 40696244, 2025). "BRAF V600E mutation characterizes more than 90% of papillary craniopharyngiomas and this gain-of-function mutation leads to the persistent activation of the RAS/RAF/MEK/ERK cascade." (PMID 39456573, 2024). "The pitfall in the use of BRAFi for papillary craniopharyngioma is the necessity of performing an initial biopsy to assess histopathology and BRAF mutation." (PMID 39456573, 2024). "Identification of specific molecular driver mutations in each type- BRAF V600E in papillary craniopharyngiomas (PCP) and CTNNB1 in adamantinomatous craniopharyngiomas (ACP) has resulted in a paradigm shift in the management of adult CPs." (PMID 39634188, 2024). "As BRAF mutations in papillary craniopharyngiomas are also ubiquitous, targeted molecular therapy was considered as an alternative to surgery and radiotherapy." (PMID 39456573, 2024). "The article will review a step-by-step management of how a positive BRAF V600E mutation status altered the course of treatment and outcome of two clinical cases of papillary craniopharyngiomas." (PMID 39634188, 2024). "Background/Objectives: The recent discovery of BRAF mutation in papillary craniopharyngiomas opened new avenues for targeted therapies to control tumour growth, decreasing the need for invasive treatments and relative complications." (PMID 39456573, 2024). "He underwent an endonasal resection of the middle fossa tumor; pathology, this time, showed a BRAF V600E mutated papillary craniopharyngioma." (PMID 39664200, 2024). "Keeping in mind that the overwhelming majority of papillary craniopharyngioma carry a BRAF V600E mutation, efforts are made to target this pathway." (PMID 39664200, 2024). "Papillary craniopharyngiomas are rare tumors prevalent to the precision oncology world due to their high rate of BRAF V600E mutations." (PMID 39664200, 2024). "The pathology confirmed papillary craniopharyngioma and on genomic sequencing revealed presence of the BRAF V600E mutation." (PMID 39634188, 2024). "Considering that a high rate of papillary craniopharyngioma exhibits a BRAF V600E mutation, the efficacy of the targeted therapy has been widely reported." (PMID 34966836, 2021). "BRAF V600E mutation has recently been identified as the principal oncogenic molecular driver of papillary craniopharyngiomas (PCP), one of the two main variants of craniopharyngioma." (PMID 35155453, 2021). "On the other hand, mutations of BRAF gene (BRAF V600E) are the main oncogenic alteration seen in papillary craniopharyngiomas; similarly, this mutation can be detected using BRAFV600E immunohistochemistry." (PMID 32676456, 2020).